FGF3 (fibroblast growth factor 3)
Diseases named in the same sentence as FGF3 in open-access papers (continued):
Sharing a sentence is not in itself a finding about the gene and the disease.
muscular dystrophy (1 paper, 2022). Muscular dystrophy (MD) refers to a group of more than 30 genetic diseases characterized by progressive weakness and degeneration of the skeletal muscles that control movement. "Although there are no REDs linked to FGF3 STRs described here, the only known disease caused by the expansion of intronic (CCTG·CAGG) tetra-nucleotide repeats is myotonic dystrophy 2 (DM2), one of the two most common forms of muscular dystrophy." (PMID 35996584, 2022).
myelocystocele (1 paper, 2023). "A small localised dilation of the closed neural tube at the level of the hindlimb buds, but not terminal myelocystocele-like phenotypes at later stages, was previously observed in Fgf3 knockout embryos." (PMID 37756583, 2023).
neuropathy (1 paper, 2022). A disorder affecting the nervous system that manifests with pain, tingling, numbness, and/or muscle weakness. "Previous studies suggested that Fgf3 may play a role in pain and neuropathy." (PMID 36264609, 2022).
Obesity (1 paper, 2019). Accumulation of substantial excess body fat. "We also found that fibroblast growth factor 3 (FGF3), upstream of KRAS, is associated with a hypomethylated DMR in its promoter region in obesity and is even further hypomethylated in CRC." (PMID 30911103, 2019).
otitis media (1 paper, 2011). Inflammation of the anatomical structures of the middle ear, which is most often caused by an infectious process. "We also observed a mild to moderate bilateral conductive hearing loss in three carriers of p.R95W, suggesting either a semi-dominant effect of this mutant allele of FGF3, otitis media, or a consequence of genetic background in these three family members." (PMID 21306635, 2011).
otodental syndrome (1 paper, 2019). Otodental syndrome is a very rare inherited condition characterized by grossly enlarged canine and molar teeth (globodontia) associated with sensorineural hearing loss. "Although some of the truncating and frameshifting mutations may appear to be loss-of-function, individuals with heterozygous complete gene deletion of FGF3 have been described with Otodental syndrome, consisting of high frequency hearing loss and large teeth, inherited in a dominant fashion." (PMID 31336982, 2019).
penile squamous cell carcinomas (1 paper, 2022). "CREBBP and FGF3 mutations have also been described in penile squamous cell carcinomas." (PMID 36564761, 2022).
scoliosis (1 paper, 2023). A congenital or acquired spinal deformity characterized by lateral curvature of the spine. "Among the genes that have been confirmed to be involved in the development of scoliosis in humans (TBX6, FGF3, LBX1, POC5, TTLL1) and vertebrates (Kif6 and Ptk), several are ciliary genes." (PMID 37239471, 2023).
secondary progressive MS (1 paper, 2013). "Recently, a randomized pilot study in humans showed that masatinib, a PDGFR, c-kit and Fgf3 inhibitor, has a moderate effect on primary progressive MS (PPMS) and relapse-free secondary progressive MS (rfSPMS)." (PMID 23437178, 2013).
spina bifida (1 paper, 2016). A congenital neural tube defect in which vertebrae are not fully formed. "However, we demonstrate that cell death does not cause the Fgf3 phenotype: blocking apoptosis via deletion of pro-apoptotic genes surprisingly increases all Fgf3 defects including causing spina bifida." (PMID 27144312, 2016). "Our work suggests that FGF3 may be a player in the complex etiology of the human birth defect, spina bifida, the failure of posterior neural tube closure." (PMID 27144312, 2016).
squamous cell carcinoma (1 paper, 2016). A carcinoma arising from squamous epithelial cells. "Potential tumor suppressor genes, also found in other squamous cell carcinomas, have been discovered in the lost regions 2q33-q37.3 (PLCD4), 3p26.3-q11.1 (RBMS3, PLCD1, and CACNA2D3) and 11q12.2-q25 (CPT1A, CCND1, FGF4/FGF3, and PPP2R1B)." (PMID 26901676, 2016).
tendinopathy (1 paper, 2021). "Furthermore, gene variants of FOXP3, FCRL3, BMP4, and FGF3 and FGF10 as well as FGFR1 were analyzed in connection with tendinopathy in competitive athletes." (PMID 34366884, 2021).
triple-negative breast carcinoma (1 paper, 2020). An invasive breast carcinoma which is negative for expression of estrogen receptor (ER), progesterone receptor (PR), and human epidermal growth factor receptor 2 (HER2).
tumor (45 papers, 1993 to 2026). "FGF3 over-expression has been detected in various tumor types, frequently associated with metastatic evolution and disease progression." (PMID 36835166, 2023). "It is also noteworthy that FGF3 amplification may be associated with multiple lung metastases and a poorly differentiated tumor." (PMID 35924239, 2022). "This is supported by scRNA-seq data showing the expression of FGFR1 and various FGF ligands (e.g., FGF3, 8, 9, 19) in tumor tissues and organoids." (PMID 39567475, 2024). "FGF3 had the highest fold change in dysplasia and tumor samples as well, 7.4 and 12.3, respectively." (PMID 39324009, 2024). "Cell function assays confirmed that FGF3 plays an important role in tumor cell proliferation, cell cycle, migration, invasion, EMT, and xenograft formation." (PMID 37496658, 2023). "Protein samples were extracted from three tumor tissues and their corresponding normal breast tissues, and the expression levels of FGF3 in normal breast tissues and SBC tissues were compared by western blot analysis." (PMID 37496658, 2023). "Our results indicate that FGF3 is highly expressed in the SBCs of TA2 mice and is associated with tumor cell proliferation, cell cycle, migration, EMT, invasion, and tumorigenesis in xenografts." (PMID 37496658, 2023). "The combination of LY2874455 and abemaciclib was necessary to completely inhibit the growth of tumor harbored FGF3/4/19/CCND1 amplification." (PMID 35814257, 2022). "Collectively, our data provide a strong rationale for clinical testing of dual targeting of FGFR and CCND1/CDK4 in NSCLC patients with FGF3/4/19/CCND1-amplification tumor resistant to gefitinib." (PMID 35814257, 2022). "Taken together, these results indicated that FGF3 and its signaling receptors are able to promote tumor growth in epithelial tissues." (PMID 35996584, 2022). "To date, several tumor cell biomarkers, including MDM2/4, epidermal growth factor receptor mutation, DNMT3A, and FGF3/4/19, have been shown to be associated with HPD." (PMID 36428951, 2022). "The most recurrent focal amplified region was 11q13.3 including the CCND1 and FGF3 genes amplified in 40% of samples (60/66 with smoking history), consistent with a region preferentially amplified on smoking related tumours." (PMID 29377909, 2018). "DMS were mapped to genes including pyruvate kinase, muscle (Pkm), β-catenin (Ctnnb1), and fibroblast growth factor 3 (Fgf3) that are known to be involved in tumor development including OSCC." (PMID 29073177, 2017). "In all, 4/16 of the neoplasia expressed Fgf3, 7/16 expressed Wnt-1, 6/16 expressed Wnt10b, and 11/16 expressed Rspo2." (PMID 23866257, 2013). "MMTV integration near the Wnt1/Wnt10b and Fgf3/Fgf4 loci can lead to the expression in the same tumor of one or the other or both genes in these clusters." (PMID 23131872, 2012). "We identified potential oncogenes, including Igf2, Hras, Fgf3, Fgf4, and Ccnd1 in this amplicon that could promote tumor growth in mBT0309." (PMID 41568176, 2026). "lnc-FGF3-4 may promote tumor cell proliferation by upregulating SHANK2 to inhibit the Hippo signaling pathway." (PMID 37538124, 2023). "Our findings suggest a neomorphic function of KLF4K409Q is the selective upregulation of FGF3 and that it may promote tumor growth." (PMID 35996584, 2022). "By real-time qPCR, we further examined the expression of selected genes (Pkm, Ppp1r13l, Vamp3, Ctnnb1, Tbc1d4, Ppp1r21, C1qtnf9, Fgf3 and Efemp2) that are known to be involved in the tumor development or potentially relevant for establishment of malignant transformation." (PMID 29073177, 2017). "Loss of CDKN2B and gain of BCL6, FGF3, and PTP4A3 predicted tumor." (PMID 22570652, 2012).
tumor (continued). "The aim of this study was to elucidate a possible association of FGF-3 copy numbers with established prognostic factors such as age, histology, FIGO stage, grading, postoperative residual tumour mass, ascites, hormone receptor content and preoperative CA 125 serum levels." (PMID 8494710, 1993). "Similarly, combinations of Fgfr2FL with Myc, Fgf3 and/or Ccnd1 cDNAs into single lentiviral constructs cooperatively shortened tumour onset after intraductal delivery, with the latencies of the Fgfr2FL-T2A-Myc and Fgfr2FL-T2A-Fgf3-P2A-Ccnd1 combinations matching Fgfr2ΔE18 single-driver latency." (PMID 35948633, 2022). "In detail, FGF1 and FGF10 were downregulated in most of the tumor types whereas FGF3, FGF5, FGF11, FGF19, FGF20, and FGF21 were upregulated in most of the tumor types." (PMID 32596330, 2020). "Supporting the notion that these modules represent specific signatures, genes known to be expressed in tumour epithelium, such as WNT targets (e.g. AXIN2, NOTUM), FGF3 and BMP4 were contained in the brown module [Suppl." (PMID 29541918, 2018). "Several previous studies demonstrated that genomic alterations such as VEGFA or FGF3/4 amplification can identify HCC patients who showed clinical responses after sorafenib treatment, although tumor biopsy specimens are required." (PMID 29258450, 2017). "We confirmed the presence of active virus in Mtv-1/NIV infected tissues and using quantitative reverse transcription PCR (qRT-PCR) found that Mtv-1/NIV induced neoplasms (tumors and hyperplasia) commonly expressed the core CIS genes Wnt1, Wnt10b, Rspo2, Fgf3." (PMID 23866257, 2013). "In addition, neither GFAP nor FGF3, two established astrocyte markers are associated with survival, indicating that these correlations are specific to gene expression, rather than a simple indication of astrocyte density present in the tumor microenvironment." (PMID 22393407, 2012). "Based on these findings, we hypothesize that upon tumor cell metastasis to the liver, the secretion of fibroblast growth factors such as FGF23 and FGF3 may stimulate the phenotypic transformation of CAF precursor cells into VCAN_eCAF." (PMID 41258075, 2025). "For example, FGFR3 was enriched greater than 8x in tumor-positive samples, while PIK3CA mutation and FGF3 amplification were never observed in post resection, negative surveillance cystoscopy samples." (PMID 36233691, 2022). "Der Tumor mit unbekanntem HPV-Status wies Amplifikationen von FGF3, FGF4, FGF19, FGF6 und FGF3 auf." (PMID 32519203, 2021). "Moreover, we detected 15 gene amplifications in six different tumor specimens, including AR, CCND1 (n = 2), FGF19 (n = 2), FGF3 (n =2), KRAS (n = 2), MYC (n = 2), CCND3, CCNE1, CDK6, and RICTOR." (PMID 33203166, 2020). "The expression of FGF3 protein in the tumor cells but not in the normal oral epithelium cells suggested that Fgf3 hypomethylation is an early response to DBP treatment." (PMID 29073177, 2017).
cancer (35 papers, 2007 to 2025). A tumor composed of atypical neoplastic, often pleomorphic cells that invade other tissues. "The specific derivative peptide FP16, designed against FGF3, can inhibit the expression of Cyclin D1 and PCNA, causing the cell cycle to be arrested at the G0/G1 phase, thereby inhibiting the proliferation of cancer cells caused by FGF3 overexpression." (PMID 41155018, 2025). "FGF3/FGFRs are also associated with cellular proliferation, infiltration, and invasiveness during the initiation and development of cancer." (PMID 32432040, 2020). "Other Int genes, such as Int-2 and 4 (Fgf3, 4), and Int-3 (Notch4), encode mitogens and regulators of development that are also misactivated in many cancers." (PMID 17895999, 2007). "It is worth mentioning that only one MMTV insertion site was found in the WGS; therefore, we can infer that FGF3 has a strong role in promoting the development of SBC, which also reflects the significance of studying the cancer-promoting mechanism of FGF3." (PMID 37496658, 2023). "In conclusion, the FGF3/FGFR1/STAT3 signaling pathway is one of the mechanisms by which FGF3 promotes cancer." (PMID 37496658, 2023). "The amplification of FGF3/4/19/CCND1 on chromosome 11q13 was found in many cancers with TKI resistance." (PMID 35814257, 2022). "Except that, the probability of some differential expression genes, such as MUC2, CLCA1, REG4, and FGF3 can be used as prognostic biomarkers in NSCLC is worth exploring because they have been reported as a biomarkers in other cancers as well." (PMID 33927719, 2021). "One study found subjects with dental agenesis had a major chance of family history of cancer and associations with AXIN2, FGF3, FGF10, and FGFR2 genes." (PMID 34378652, 2021). "These DMS were mapped to genes including Fgf3, Ctnnb1 and Pkm, known to be involved in cancer-related pathways." (PMID 29073177, 2017). "Two of the individual CTCs (CTC1 and CTC2) and the CTC pool had homogenous copy-number profiles, and included amplification on 1q and 8q (MYC), 11q (CCND1, FGF3, FGF4) and allelic loss of regions including several cancer genes on 3p (BAP1), 13q(RB1, BRCA2) and 17p (MAP2K4)." (PMID 36088510, 2022). "Most of CEDGs like CCND1, ALDH3B1, MYEOV were frequently hypomethylated in cancer, while FGF3, FGF4, MRGPRF and CPT1A were hypermethylated in most cancers." (PMID 40478912, 2025). "FGF3, derived from the 5′AUG codon (239 amino acid residues in humans), is secreted and acts in a paracrine manner during embryogenesis and cancer pathology." (PMID 39766329, 2024). "The co-amplification of FGF3, FGF4, FGF19, and CCND1was also observed in another pan-cancer study from the United States." (PMID 35494043, 2022). "Several known cancer-related genes, such as CCND1, FGF4, FGF3, and CTTN, have been mapped to the 11q13 chromosome region." (PMID 24930674, 2014). "FGF3/4/19 amplification has also been reported as a predictive marker of cancer highly progressive disease (HPD) in a variety of treatment lines for HCC and other cancers." (PMID 38665910, 2024). "Amplification of FGF3/4/19 and CCND1 has been revealed in various cancers." (PMID 35814257, 2022). "Finally, since FGF3/4/19/CCND1 genes are frequently amplified in many solid cancers, it is worthy to test this therapeutic strategy in other cancers beyond NSCLC." (PMID 35814257, 2022). "We did not see a significant correlation of cancer FGF3 expression levels with clinical or pathological parameters, although the sample size is small, tempering this conclusion." (PMID 26019137, 2015). "However, the ORAOV1 gene was identified within chromosomal band 11q13, which includes several known cancer-related genes such as CCND1, FGF4, FGF3, and CTTN." (PMID 24930674, 2014).
skeletal dysplasia (1 paper, 2016). Any Mendelian diseases that affects growth and development of the skeleton. "TD is the most frequent lethal skeletal dysplasia caused by mutation of the fibroblast growth factor 3 (FGFR3) gene." (PMID 27006844, 2016).
FGF3 also shares sentences with these, for which no sentence is quoted: lung carcinoma (3 papers); Microdontia (3); cholangiocarcinoma (2); colorectal cancer (2); endometrial carcinoma (2); Hypodontia (2); lacrimo-auriculo-dento-digital syndrome (2); oral cancer (2); pancreatic cancer (2); prostate carcinoma (2); acral melanoma (1); Acute otitis media (1); allergic rhinitis (1); childhood asthma (1); chronic obstructive pulmonary disease (1); clear cell sarcoma of the kidney (1); developmental arrest (1); diabetic retinopathy (1); epilepsy (1); Esophageal Neoplasms (1); esophageal squamous cell carcinoma (1); esophagus cancer (1); essential tremor (1); fibrosis (1); gall bladder cancer (1); hypochondroplasia (1); Intellectual disability (1); lymphoma (1); microcephaly (1); myotonic dystrophy 2 (1).
A further 11 diseases each share a sentence with FGF3 in 1 paper.